CTSLP4 (cathepsin L pseudogene 4)
Synonyms: bA564C4.3; OTTHUMG00000018237; formerly CTSLL4; CTSL1P4
Gene: Transcribed unprocessed pseudogene on chromosome 10 (50,705,380 to 50,708,906, reverse strand). Ensembl gene ENSG00000230011.
Diseases named in the same sentence as CTSLP4 in open-access papers:
CTSLP4 is named in the same sentence as 2 diseases in open-access papers, as found by Europe PMC text mining. Sharing a sentence is not in itself a finding about the gene and the disease. The quoted sentences say what the papers report.
gastric cancer (1 paper, 2022). A primary or metastatic malignant neoplasm involving the stomach. "Lnc-CTSLP4 is low expressed in tumor tissues, acting as an antioncogene in gastric cancer." (PMID 35322746, 2022).
tumor (2 papers, 2022 to 2025). "Furthermore, Lnc-CTSLP4 was found to upregulate E-cadherin expression and downregulate N-cadherin levels in these cells, leading to increased cell-cell adhesion at the leading edge of the tumor infiltrate." (PMID 40760598, 2025).